GAP43 (growth associated protein 43)
Description:
This protein is associated with nerve growth. It is a major component of the motile 'growth cones' that form the tips of elongating axons. Plays a role in axonal and dendritic filopodia induction.
Synonyms: B-50; PP46; GAP-43
Tractability: Antibody: UniProt places it where antibodies can reach, with high confidence; its Gene Ontology location is reachable by antibodies, with high confidence; the Human Protein Atlas places it where antibodies can reach. PROTAC: ubiquitination databases record sites on it; its protein half-life has been measured.
Gene: Protein-coding gene on chromosome 3 (115,623,510 to 115,721,490, forward strand). Ensembl gene ENSG00000172020.
Subcellular location: Cell membrane; Cell projection, growth cone membrane; Synapse; Cell projection, filopodium membrane; Perikaryon; Cell projection, dendrite; Cell projection, axon; Cytoplasm
Subcellular location (Human Protein Atlas): Plasma membrane
Pathways (Reactome):
Developmental Biology: L1CAM interactions
Gene Ontology:
Molecular function: protein binding; calmodulin binding; lysophosphatidic acid binding; phosphatidylinositol phosphate binding; phosphatidylserine binding
Biological process: regulation of filopodium assembly; axon choice point recognition; phospholipase C-activating G protein-coupled receptor signaling pathway; response to wounding; tissue regeneration; nervous system development; regulation of growth; regulation of postsynaptic specialization assembly; response to auditory stimulus
Cellular component: filopodium membrane; plasma membrane; synapse; cytoplasm; perikaryon; postsynaptic density; axon; cell periphery; dendrite; GABA-ergic synapse; growth cone membrane; presynapse
Genetic constraint (gnomAD): Loss-of-function variants: 2 observed, 17.6 expected, observed/expected ratio (o/e) 0.11, 90% interval 0.045 to 0.36. The upper end of that interval is the gene's LOEUF score, 0.36, which puts it in group 1 of 6, group 1 being the genes least tolerant of losing a copy. Missense variants: 265 observed, 287.52 expected, observed/expected ratio (o/e) 0.92, 90% interval 0.83 to 1.02. Synonymous variants: 107 observed, 109.13 expected, observed/expected ratio (o/e) 0.98, 90% interval 0.84 to 1.15.
Homologues: Orthologues: chimpanzee GAP43 (97% identical), macaque GAP43 (97% identical), dog GAP43 (79% identical), pig GAP43 (78% identical), mouse Gap43 (77% identical), rat Gap43 (77% identical), guinea pig GAP43 (54% identical), tropical clawed frog gap43 (46% identical), zebrafish gap43 (31% identical). Paralogues in human: SPA17 (12% identical), RIIAD1 (4% identical).
Diseases named in the same sentence as GAP43 in open-access papers:
GAP43 is named in the same sentence as 158 diseases in open-access papers, as found by Europe PMC text mining. Sharing a sentence is not in itself a finding about the gene and the disease. The quoted sentences say what the papers report.
Stroke (53 papers, 2008 to 2026). Sudden impairment of blood flow to a part of the brain due to occlusion or rupture of an artery to the brain. "The initial increase in GAP-43 during the nine first days was associated to stroke severity, the degree of white matter lesions and atrophy and correlated positively with infarct size (rs = 0.65, P = 0.001)." (PMID 30526557, 2018). "In the first 9 days after stroke, the increase in GAP-43 concentration was significantly associated with change in stroke severity as measured by the modified SSI scale (r = 0.49, P = 0.01)." (PMID 30526557, 2018). "Central administration of FGF-2 within 24 hr of experimental stroke has been shown to improve motor recovery and upregulate growth-associated protein 43, a marker of axonal growth." (PMID 25229819, 2014). "In addition, the expression of synaptic plasticity‐associated proteins Synaptophysin, PSD95 and GAP43 in the hippocampus was significantly decreased following stroke, which were upregulated by IL‐2:IL‐2 Ab complex and inhibited by 4‐CIN." (PMID 41552852, 2026). "Furthermore, overexpression of C3a under the glial fibrillary acidic protein (GFAP) promoter leads to increased production of GAP43, an axonal marker associated with post-stroke neurite extension." (PMID 41002405, 2025). "Elevated GAP-43 expression is also linked to axonal sprouting in the barrel cortex after a stroke." (PMID 38397420, 2024). "Furthermore, an increase in GAP-43 was linked to optogenetic-induced functional recovery in the primary motor cortex after a stroke." (PMID 35349008, 2023). "Additionally, an increase in GAP-43 was associated with optogenetic-induced functional recovery from stroke in the primary motor cortex." (PMID 33015061, 2020). "Considering the function of GAP-43, it may also be induced by neuronal damage caused by stroke, traumatic brain injury and epilepsy." (PMID 30526557, 2018). "Interestingly, C21 has recently been shown to attenuate early mortality and increase BDNF, TrkB, and the axonal growth and regeneration marker growth-associated protein 43 (GAP-43) after stroke." (PMID 29543776, 2018). "EE intervention increased level of SYN and GAP‐43 in the bilateral hippocampus and the right peri‐hippocampal cortex after stroke." (PMID 37752881, 2024). "In rodent stroke models, the use of antisense oligonucleotides targeting GAP-43 was found to counteract the enhancement of functional recovery induced by basic fibroblast growth factor." (PMID 38397420, 2024). "We observed a remarkable reduction in MAP2, RBFOX3, and GAP43 levels in the ET-1 group (all p < 0.01), suggesting a severe axonal injury occurred after stroke." (PMID 39697542, 2024). "Optogenetic stimulation increases GAP-43 expression, similar to other long-term optogenetic studies following stroke (Cheng et al2014, Shah et al2017)." (PMID 37524080, 2023). "On the other hand, levels of GAP-43 were upregulated in other brain disorders including stroke, schizophrenia and bipolar disorder." (PMID 35943710, 2022). "A previous study reported that improvement of memory ability in rats with post-stroke rehabilitation was associated with the increase of BDNF/TrkB, as well as GAP-43 and PSD-95." (PMID 36076858, 2022). "The stroke-induced increase in GAP-43 expression in the peri-infarct region was reduced in mice constitutively lacking C3aR, while it was further increased when C3a was expressed in reactive astrocytes or administered intranasally starting 7 days after stroke." (PMID 34379293, 2021). "In a different rodent model of stroke, antisense oligonucleotides to GAP-43 abolished the enhancement of functional recovery induced by the basic fibroblast growth factor." (PMID 33015061, 2020). "After an injury to the CNS such as stroke, there is upregulation of GAP-43 which occurs between seven days and three weeks after the ischaemic injury." (PMID 32617098, 2020).
Stroke (continued). "Such beneficial upregulation of NGF and BDNF was accompanied by an increase in GAP-43 levels when optogenetic stimulations were provided after stroke." (PMID 33015061, 2020). "GAP-43 immunostaining was used as a surrogate measure of axon growth and/or terminal sprouting in stroke models." (PMID 31781025, 2019). "Additional studies are required to further evaluate the value of GAP-43 as a stroke biomarker and elucidate its connections to injury progression and clinical outcome." (PMID 30526557, 2018). "GSE16561 database analysis revealed that both Ngb and GAP43 were upregulated in the blood of patients after stroke." (PMID 29416029, 2018). "The concentration of GAP-43 was measured in longitudinal CSF samples from 28 stroke patients prospectively collected on days 0–1, 2–4, 7–9, 3 weeks, and 3–5 months after ischemia and cross-sectionally in 19 controls." (PMID 30526557, 2018). "Nonetheless, we show for the first time that changes in CSF GAP-43 after stroke are connected to clinical measures." (PMID 30526557, 2018). "Studies have showed that GAP-43 contributes to the persistent post-stroke axon sprouting by awakening the neurons in the peri-infarct cortex." (PMID 29487502, 2018). "Increased GAP-43 concentration was detected from day 7–9 to 3 weeks after stroke, compared to day 1–4 and to levels in the control group (P = 0.02 and P = 0.007)." (PMID 30526557, 2018). "The transient increase of CSF GAP-43 appearing most intensely at 1–3 weeks after stroke is important to take into account when used as a biomarker for other neurodegenerative diseases." (PMID 30526557, 2018). "We evaluated CSF GAP-43 concentration in longitudinally sampled stroke patients to 1) further determine the pathogenic mechanisms of increased CSF GAP-43 concentration, and 2) investigate the biomarker potential of CSF GAP-43 after stroke." (PMID 30526557, 2018). "As stroke is likely to occur in a fraction of the study population during a drug trial period, it would be important to take into consideration that CSF GAP-43 is transiently increased after stroke affecting outcome levels." (PMID 30526557, 2018). "Although this novel C3a result is surprising, a recent paper has suggested that C3a and C3aR positively regulate axon growth-associated protein GAP43 as well as synapsin+ and VGLUT1+ synaptic density following experimental photothrombotic stroke in mice." (PMID 29018286, 2017). "In conclusion, we provide the first evidence that EA enhances rehabilitation against stroke by regulating epigenetic changes to directly act on its targets, such as the miR-181b/PirB/RhoA/GAP43 axis, which is a novel mechanism of EA therapy." (PMID 27966582, 2016). "Growth associated protein 43 (GAP43), a neuronal growth cone marker, is also induced in peri-infarct cortex after stroke." (PMID 28082858, 2016). "GAP43 expression following stroke is strikingly similar to staining of GAP43 in first and second postnatal weeks in the barrel cortex." (PMID 18179704, 2008). "GAP43 is shown to be involved in post-stroke axonal sprouting and is important in critical stages of neurodevelopment of the barrel cortex." (PMID 18179704, 2008). "Similarly, target brain regions were selected based on rs‐fMRI results to detect the expression of axonal marker GAP43 in rats with large stroke, including bilateral M1, M2, Cg1, CC and right sensory cortex, Ent, and STR." (PMID 39496513, 2024). "Several in vivo studies have formerly suggested that GAP-43 translation may also be triggered by neuronal injury resulting from conditions like stroke, traumatic brain injury, and epilepsy." (PMID 39215335, 2024). "Additionally, higher GAP-43 levels are connected to the optogenetic-induced functional recovery of the primary motor cortex after stroke." (PMID 38397420, 2024). "Therefore, GAP-43 is considered to be a sensitive marker of axon sprouting and prolongation in an after-stroke model." (PMID 36817860, 2023).
Stroke (continued). "Elevated levels of IL-6 and TNF-α in the spinal cord after stroke upregulate the concentrations of GAP-43 (growth-associated protein 43), NT-3 (neurotrophin-3), and BDNF, all of which are known to be involved in spinal axonal plasticity and lead to better spontaneous post-stroke recovery." (PMID 33042113, 2020). "BLI, based on collecting light released from transgenic animals carrying luciferase reporters when injected with luciferin, was used to monitor the activity of Gap43 promoter (Gap43-luc/gfp transgenic mouse) as a marker of axonal repair and outgrowth to assess post-stroke axonal remodeling." (PMID 30808918, 2019). "CSF GAP-43 could become useful as a quantitative measure of the regenerative response during recovery, which should simplify comparison and evaluation of both stroke treatments and rehabilitation strategies." (PMID 30526557, 2018). "Although CSF GAP-43 was previously found largely selective for Alzheimer’s disease among neurodegenerative diseases, it may be altered by yet other conditions besides stroke." (PMID 30526557, 2018). "At 3–5 months after stroke GAP-43 returned to admission levels." (PMID 30526557, 2018). "Moreover, electroacupuncture can enhance rehabilitation against stroke by targeting miR-181b/PirB/ RhoA/GAP43 axis and leading to epigenetic changes." (PMID 30579356, 2018). "Our findings also suggest that CSF GAP-43 may be a marker of neuronal injury responses in stroke and urge for additional studies confirming the potential of CSF GAP-43 to reflect severity and outcome of stroke in larger cohorts." (PMID 30526557, 2018). "The CSF GAP-43 concentration in control subjects was similar to most stroke patients at admission (Day 0–1, Day 2–3) and the following increase during the first 9 days after stroke indicate that increased CSF GAP-43 results from a delayed or progressing process." (PMID 30526557, 2018). "GAP-43 is upregulated following stroke and traumatic brain injury." (PMID 29255203, 2017). "BLI could show that the nervous tissue-specific GAP-43 is silent in adult neurons, but up-regulated after neural injury and contributes to neurite outgrowth as part of the regeneration process after stroke." (PMID 25177269, 2014). "Indeed, C3aR knockout mice showed a reduction in GAP43 indicating that C3a may enhance neurogenesis and synaptic plasticity after stroke." (PMID 41002405, 2025). "Similarly, in a rat model of stroke, CIMT resulted in the downregulation of this signaling pathway in the region of the lesioned cortex and the upregulation of markers such as growth-associated protein-43, synaptophysin, vGlut1, and postsynaptic density-95 in the denervated cervical spinal cord." (PMID 39273353, 2024). "The potential for FGF-2 as a neurorestorative adjunct in stroke was first demonstrated in studies in which central administration of FGF-2 within 24 hr of MCAO induced improved motor recovery and the upregulation of growth-associated protein 43, a marker of axonal growth." (PMID 25229819, 2014). "In the present study, CIMT increased the expression of GAP43 and PSD95, mainly in the contralesional RN after a large-area stroke." (PMID 40166667, 2025). "Optogenetic stimulations post-stroke resulted in a beneficial increase in NGF, BDNF, and GAP-43 levels." (PMID 38397420, 2024). "In summary, we determined that activation of the mTOR signaling pathway and increased expression of GAP-43 and SYN after stroke are beneficial to axonal regeneration and neurological recovery." (PMID 36440366, 2022). "EA pretreatment can increase the expression of GAP-43 and BDNF and alleviate ischemic injury and promote axonal regeneration, thereby providing protection for functional recovery following stroke." (PMID 36440366, 2022). "The upregulation of GAP-43 and BASP1 also correlated with axonal sprouting after stroke in the barrel cortex." (PMID 33015061, 2020).
Stroke (continued). "The reason for the long sample storage time is that a stable CSF GAP-43 quantification method was just recently developed and this evaluation of CSF GAP-43 in longitudinal stroke samples was possible through a previous established collaboration." (PMID 30526557, 2018). "Furthermore, even though CSF GAP-43 concentration could become useful as a biomarker of neuronal injury after stroke, it is equally important to examine confounding conditions that may affect the use of CSF GAP-43 as a biomarker or outcome measurement in other neuronal diseases." (PMID 30526557, 2018). "Further, we also report that GAP43, a putative marker of axonal growth was elevated following PEG-IGF-I treatment 3 hrs post-stroke in vivo." (PMID 28325900, 2017). "In this proteomics study, the neurogenesis-related proteins, Actn1, Gap43, Gfap, and neurofascin (Nfasc) were upregulated after the CIR-induced stroke (Neurogenesis sector)." (PMID 26492191, 2015). "The results showed that CIMT promoted motor recovery after a stroke, increased levels of GAP43 and PSD95 in the contralesional but not ipsilesional RN, and increased projections from the MC to the bilateral RN." (PMID 40166667, 2025). "Numerous research findings indicate that proteins such as BDNF, GAP43, PSD95, and synaptophysin play critical roles in neurogenesis, synaptic repair, and neural plasticity, all of which are crucial for functional recovery post-stroke." (PMID 39519132, 2024). "Recent studies have provided evidence that the neuroprotective effects of mTOR on stroke may be due to its ability to increase PSD95 and GAP-43 protein levels or promote neuronal structural stability in peri-infarct regions." (PMID 35211177, 2022). "Alongside expression of RTN4A, comprising 76% total astrocytes in the injured cohort and 21% in control, we observed robust expression of GAP43, CD44 and KLF6, with both the percent of nuclei expressing these genes and the overall level of expression significantly increased after stroke." (PMID 34824275, 2021). "CSF GAP-43 concentration is elevated in Alzheimer’s disease patients; however, patients suffering from stroke have not been studied previously." (PMID 30526557, 2018). "Recognizing the critical roles of proteins such as GAP43, PSD95, and synaptophysin in synaptic plasticity and recovery following stroke, we aimed to assess whether rNPFF treatment could increase the expression of these markers, thereby supporting synaptic integrity under ischemic conditions." (PMID 39519132, 2024). "However, there seems to be no study as yet in humans reporting on the role GAP-43 has on the recovery of motor function in stroke following CIMT." (PMID 32617098, 2020). "This suggests that although neurogenesis and post-stroke recovery may occur in tandem, this may be coincidental, with recovery being more directly related to the upregulation of a variety of growth-promoting factors such as BDNF and GAP43." (PMID 30050416, 2018). "However, GAP-43 quantification has to our knowledge not been measured in any body fluids of stroke patients." (PMID 30526557, 2018). "Furthermore, GAP-43 may be a marker of neuronal responses after stroke and additional studies confirming the potential of CSF GAP-43 to reflect severity and outcome of stroke in larger cohorts are warranted." (PMID 30526557, 2018). "Additionally, in rodent stroke models, a rapid induction of both GAP-43 gene and protein expression in the brain is reportedly present already at day one after ischemia and sustained up to 28 days and GAP-43 was suggested to be an early and sensitive marker of neuronal damage after ischemia." (PMID 30526557, 2018).